NPAS3 (neuronal PAS domain protein 3)
Description:
May play a broad role in neurogenesis. May control regulatory pathways relevant to schizophrenia and to psychotic illness (By similarity).
Synonyms: bHLHe12; MOP6; PASD6
Tractability: No criterion of Open Targets' tractability assessment is met for any kind of drug.
Gene: Protein-coding gene on chromosome 14 (32,934,396 to 33,820,863, forward strand). Ensembl gene ENSG00000151322.
Subcellular location: Nucleus
Subcellular location (Human Protein Atlas): Nucleoplasm
Gene Ontology:
Molecular function: protein binding; DNA-binding transcription factor activity, RNA polymerase II-specific; protein heterodimerization activity; RNA polymerase II transcription regulatory region sequence-specific DNA binding; protein dimerization activity
Biological process: positive regulation of DNA-templated transcription; regulation of transcription by RNA polymerase II; regulation of DNA-templated transcription
Cellular component: nucleoplasm; nucleus; chromatin
Genetic constraint (gnomAD): Loss-of-function variants: 8 observed, 50.39 expected, observed/expected ratio (o/e) 0.16, 90% interval 0.092 to 0.29. The synonymous counts are far from expectation, so gnomAD's model fits this gene poorly and the ratio says little. Missense variants: 978 observed, 1,045.5 expected, observed/expected ratio (o/e) 0.94, 90% interval 0.89 to 0.99. Synonymous variants: 551 observed, 458.03 expected, observed/expected ratio (o/e) 1.2, 90% interval 1.12 to 1.29.
Homologues: Orthologues: chimpanzee NPAS3 (98% identical), macaque NPAS3 (97% identical), rabbit NPAS3 (96% identical), pig NPAS3 (96% identical), dog NPAS3 (96% identical), mouse Npas3 (93% identical), rat Npas3 (90% identical), guinea pig NPAS3 (76% identical), zebrafish NPAS3 (75% identical), tropical clawed frog npas3 (73% identical), Drosophila melanogaster trh (35% identical), Drosophila melanogaster sima (19% identical), and 1 more. Paralogues in human: NPAS1 (32% identical), SIM2 (24% identical), SIM1 (23% identical), HIF1A (21% identical), EPAS1 (21% identical), HIF3A (18% identical), NPAS4 (14% identical).
Diseases named in the same sentence as NPAS3 in open-access papers:
NPAS3 is named in the same sentence as 41 diseases in open-access papers, as found by Europe PMC text mining. Sharing a sentence is not in itself a finding about the gene and the disease. The quoted sentences say what the papers report.
schizophrenia (29 papers, 2012 to 2025). A major psychotic disorder characterized by abnormalities in the perception or expression of reality. "Among these potential targets is Npas3, a transcription factor associated with neuropsychiatric disorders characterized by impaired neuronal plasticity, such as schizophrenia." (PMID 39846680, 2025). "TET1 (ten–eleven translocation methylcytosine dioxygenase 1) has NPAS3 (neuronal Per-Arnt-Sim 3) as a target that is associated with schizophrenia essential for synaptic plasticity in turn affecting learning and retention." (PMID 39299805, 2024). "A soluble form of Neuronal PAS Domain Protein 3 in serum appears to be associated with schizophrenia, and its gene showed pleiotropic effects among schizophrenia, MDD, and bipolar disorder." (PMID 39457114, 2024). "In that case, a chromosomal translocation disrupting the NPAS3 gene was present in both the mother and daughter affected with schizophrenia, which allowed researchers to associate the gene with mental impairment." (PMID 36430976, 2022). "Initially, the association of NPAS3 with schizophrenia was demonstrated in one interesting family case of schizophrenia, which was diagnosed in both mother and daughter." (PMID 36430976, 2022). "Subsequent studies have further linked NPAS3 aberrations to multiple human psychiatric and neurodevelopmental disorders, including schizophrenia, bipolar disorder, major depression, attention-deficit/hyperactivity disorder, and intellectual disability." (PMID 36313621, 2022). "For example, it was established that specific NPAS3 haplotypes increase the risk of both schizophrenia and bipolar disorder." (PMID 36430976, 2022). "Recently, neuronal PAS domain protein 3 (NPAS3), a known genetic risk factor for schizophrenia, was implicated through a V304I point mutation in a family with major mental illness." (PMID 34834422, 2021). "NPAS3 was originally implicated in mental illness due to a chromosomal translocation that disrupted the NPAS3 gene in a mother with schizophrenia, as well as in her daughter, who had schizophrenia and mild learning difficulties." (PMID 34834422, 2021). "Specifically, an ultrarare missense mutation, discovered in a family with schizophrenia and related disorders, was suggested to induce or enhance the aggregation propensity of NPAS3." (PMID 34834422, 2021). "Although the V304I mutation located in the PAS linker did not alter the protein’s molecular function, mutation in the disordered region of NPAS3 led to the aggregation of this protein, which resulted in schizophrenia." (PMID 33799876, 2021). "NPAS3 aggregation, previously implicated in schizophrenia, therefore appears to be much more widespread than expected." (PMID 34834422, 2021). "Single nucleotide variation affecting the coding regions of NPAS3 have been associated with neuropsychiatric disorders, including schizophrenia." (PMID 30509165, 2018). "Since its discovery as a potential “schizophrenia gene”, NPAS3 has been robustly associated with neurodevelopmental and neuropsychiatric disorders commonly characterized by alterations in white matter connectivity, and intellectual disability." (PMID 30509165, 2018). "We do not find significant differences in the percentages of proteins associated with ID, ASD or schizophrenia between the interactomes of starting transcription factors Tcf4, Olig2, Npas3, Sox2 (P-value >0.2 for all MD categories)." (PMID 28375211, 2017). "Various gene specific and genome-wide case-control association studies have linked single nucleotide polymorphisms in the NPAS3 gene with increased risk of schizophrenia, major depression and bipolar disorder." (PMID 27877109, 2016). "The larger genetic study (conducted at two different sites in Canada) is currently expanding on our earlier preliminary work examining NPAS3 variants in schizophrenia." (PMID 24674381, 2014).
schizophrenia (continued). "Our case–control study identified significant changes in the NPAS3 coding sequence with a positive association to schizophrenia." (PMID 24674381, 2014). "A decrease in adult neurogenesis was reported in mutant mice of schizophrenia-associated genes such as reeler mice, NPAS3-KO mice and DISC1 knockdown mice." (PMID 24528488, 2014). "Further molecular studies indicated that this breakpoint disrupted the neuronal Per-Arnt-Sim 3 (NPAS3) gene, indicating a potential causative or contributory role to schizophrenia." (PMID 24674381, 2014). "This study will help to establish the contribution of the NPAS3 gene and its variants to brain tissue abnormalities in schizophrenia." (PMID 24674381, 2014). "NPAS3 is a transcription factor expressed in the brain and implicated in psychiatric disorders including schizophrenia." (PMID 23717195, 2013). "Additionally, Npas3 target genes were found to be significantly enriched in genes associated with schizophrenia, autism, and intellectual disability." (PMID 39846680, 2025). "It is possible that impaired neuronal radial migration and laminar cell fate commitment caused by Npas3 deficiency may contribute to the pathology of schizophrenia." (PMID 36313621, 2022). "NPAS3, expressed by GABAergic interneurons, has been shown to be an important transcription factor during neurogenesis; chromosomal aberrations encompassing this gene are associated with schizophrenia and mental retardation." (PMID 31311581, 2019). "Genome-wide studies have identified NPAS3 as associated with bipolar disorder and schizophrenia." (PMID 30509165, 2018). "The specific goals are: 1) to extend our case control study; 2) to carry out extensive evaluation of participants with schizophrenia; 3) to assess the association of NPAS3 variation with clinical presentation and cognitive function; 4) to develop molecular assays to measure NPAS3 variant function." (PMID 24674381, 2014). "Our hypothesis that NPAS3 variation may alter brain function and contribute to schizophrenia is supported by observations in Npas3 deficient mice." (PMID 24674381, 2014). "Specific NPAS3 variants have been observed at an increased frequency in schizophrenia." (PMID 24674381, 2014). "This study will evaluate the hypothesis that the severe reductions in neural precursor cell proliferation in the dentate gyrus will be present to some degree in patients carrying schizophrenia-associated NPAS3 variants and less so in other patients." (PMID 24674381, 2014). "While most of the proteins so far implicated as aggregating in chronic mental illnesses (schizophrenia in all cases plus, in some instances, also bipolar disorder and/or major depressive disorder) have been identified directly from patient brain samples, NPAS3 was implicated indirectly." (PMID 34834422, 2021). "Additionally, NPAS3 has been linked to schizophrenia and bipolar disorder, CLSTN2 has been associated with memory performance and with Alzheimer’s disease, and RBFOX1 (A2BP1) has been very recently discovered as a splicing regulator of neuronal excitation and calcium homeostasis in the brain." (PMID 22888310, 2012). "Seven switch genes, NPAS3, ARHGAP15, LGALS3BP, DPP10, SMYD3, CPXCR1, and HLA-DRB5 were associated with known risk factors for schizophrenia." (PMID 36982982, 2023). "Npas3 was first identified as a candidate gene for schizophrenia through the analysis of chromosome translocation in a small family with schizophrenia." (PMID 36313621, 2022). "Of the seven schizophrenia patients with above background levels of NPAS3 in their blood serum, all had a diagnosis of paranoid schizophrenia according to ICD-10 (code F20.0)." (PMID 34834422, 2021). "While aggregation of NPAS3 occurs in many individuals, study is now needed to determine if it is more generally enhanced in schizophrenia patients, as well as if this correlates with altered levels of NPAS3 detected in the blood." (PMID 34834422, 2021).
schizophrenia (continued). "We also detected NPAS3 in the blood serum of individuals, being more prominent in a subset of individuals with schizophrenia." (PMID 34834422, 2021). "While no indication of NPAS3 aggregation was seen in the serum, soluble NPAS3 was detected, and was more prevalent in patients with schizophrenia than in those with major depressive disorder or controls." (PMID 34834422, 2021). "Disruption of the NPAS3 gene carried by a Scottish mother and daughter diagnosed with schizophrenia and mild learning disability provided the first indication of the role of this gene in psychiatric illness." (PMID 27877109, 2016). "Further support for NPAS3 variation in brain dysfunction came from a separate and concomitant case–control study using larger cohorts of individuals with schizophrenia (n = 386) or bipolar disorder (n = 368)." (PMID 24674381, 2014). "We are currently completing a nationally funded genetic study at two different sites, in order to extend our previous case control study and continue the evaluation of the NPAS3 gene in schizophrenia." (PMID 24674381, 2014). "The first report described the consequences of disrupting Npas3 and the closely related Npas1 gene, followed by two descriptions of the Npas3 knockout mice that are particularly relevant to schizophrenia." (PMID 24674381, 2014). "Likewise, NPAS3, ARHGAP15, LGALS3BP, DPP10, SMYD3, CPXCR1, and HLA-DRB5 were associated with known risk factors for schizophrenia." (PMID 36982982, 2023). "NPAS3, encoding neuronal PAS domain protein, has been implicated in neurogenesis, general cognitive function, psychiatric disorders like schizophrenia, and has protein aggregation potential." (PMID 36609403, 2023). "It is curious that the presence of this NPAS3 in the blood correlated only with schizophrenia, for which NPAS3 aggregation was implicated, but not with major depressive disorder." (PMID 34834422, 2021). "It would be extremely interesting to know to investigate in a larger sample, whether high levels of serum NPAS3 correlate either with specific subtypes of schizophrenia, or with the severity of specific symptoms." (PMID 34834422, 2021). "Irregularities have been reported in Npas3 knockout mice and are hypothesized to also occur in individuals with schizophrenia." (PMID 24674381, 2014). "In addition, NPAS3 protein levels were reduced in the dorsolateral prefrontal cortex of some patients with schizophrenia." (PMID 24674381, 2014). "FGF signalling disturbances in mood disorders might be indirect, since the disruption of schizophrenia-associated proteins, such as the neuronal PAS domain protein 3 (NPAS3), correlates with a dramatic reduction in FGFR1 mRNA, and NPAS3 deficiency behaviourally resembles FGFR1 knock-out mice." (PMID 33860438, 2021). "The neuronal PAS domain proteins NPAS1 and NPAS3 are members of the basic helix-loop-helix-PER-ARNT-SIM (bHLH-PAS) family, and their genetic deficiencies are linked to a variety of human psychiatric disorders including schizophrenia, autism spectrum disorders and bipolar disease." (PMID 27782878, 2016). "Interestingly, mice lacking Npas3, a genetic risk factor for schizophrenia, have SGZ proliferation deficits that accompany a thinning of the dentate gyrus and a loss of dendritic complexity in the mature neurons extending processes into the molecular layer and CA3." (PMID 25272038, 2014). "In this first study to look for NPAS3 aggregation in brain tissue, although not in this case specifically in schizophrenia patients, we examined insular cortex samples from 40 individuals." (PMID 34834422, 2021). "Similar to NPAS3, VGF plays a major role in depression, bipolar disorder and schizophrenia." (PMID 27877109, 2016). "However, there are few human variants in NPAS3 and none in NPAS4 that have been associated with schizophrenia or neurodevelopmental disorders." (PMID 33758288, 2021).
schizophrenia (continued). "The analogy between humans with NPAS3-related schizophrenia and mouse models of the illness might not be straightforward, however." (PMID 24674381, 2014).
bipolar disorder (6 papers, 2012 to 2024). A disorder of the brain that causes unusual shifts in mood, energy, activity levels and the ability to carry out day-to-day tasks. "It is interesting that the NPAS3 gene has been associated with bipolar disorder and that it is also expressed differently in the dorsolateral prefrontal cortex during bipolar disorder." (PMID 36430976, 2022).
Intellectual disability (6 papers, 2017 to 2025). "NPAS3 was originally characterized in humans as the causative locus of intellectual disability and psychosis in a Scottish family, as it was broken by a reciprocal translocation that segregated with disorder." (PMID 30509165, 2018). "NPAS3 is a promising candidate gene, as it has a role in neurodevelopment, and disruptions of this gene have been associated with psychiatric and intellectual disability phenotypes." (PMID 28093568, 2017). "Interestingly, a frameshift mutation in NPAS3 has recently been reported at amino acid 214 in an individual with intellectual disability." (PMID 34834422, 2021). "Disruption of the human NPAS3 gene by the reciprocal translocation at 14q13 has been first reported in a family with intellectual disability and schizotypal features, indicating that disruption of the NPAS3 gene may contribute to the origin and development of psychiatric disorders." (PMID 36313621, 2022).
astrocytomas (5 papers, 2013 to 2022). "In consist with our results, previous studies in malignant astrocytomas have shown that loss of NPAS3 expression was associated with the high proliferation of malignant astrocytomas in humans, while overexpression of NPAS3 in malignant glioma cell lines significantly decreased proliferation." (PMID 36313621, 2022). "In astrocytomas, NPAS3 is reported as a tumor suppressor, which is involved in cell cycles, apoptosis, and cell migrations." (PMID 27156852, 2016). "A recent study supported the hypothesis that NPAS3 acts as a putative tumor suppressor during astrocytoma progression." (PMID 26902966, 2016). "In addition, NPAS3 was recently shown to act as a tumor suppressor in astrocytomas, with a possible role in glioblastoma progression and proliferation." (PMID 23717195, 2013). "Absence of NPAS3 expression in astrocytomas is a negative prognostic marker for survival." (PMID 23628382, 2013).
depression (3 papers, 2016 to 2021). "We therefore cannot rule out the possibility that a more closely matched set of controls may have revealed a significant effect on serum NPAS3 in major depressive disorder." (PMID 34834422, 2021). "This may correlate with the lack of specific NPAS3 aggregation in insular cortex samples patients with major depressive disorder and victims of suicide, seen here." (PMID 34834422, 2021).
glioblastoma (3 papers, 2013 to 2025). The most malignant astrocytic tumor (WHO grade IV). "The absence of NPAS3 expression in glioblastomas (a type of brain cancer) was reported to be associated with shorter OS." (PMID 40535770, 2025).
neuroblastoma (3 papers, 2021 to 2025). Neuroblastoma (NB) is the most common solid, extracranial childhood tumor. "Notably, application of oxidative stress to the neuroblastoma cells caused a significant reduction in cells that only displayed NPAS3 in the nucleus." (PMID 34834422, 2021). "Importantly, in a neuroblastoma cell model, it was shown that NPAS3 aggregation is enhanced under oxidative stress, which may suggest a link between disrupted redox homeostasis and conformational changes of the NPAS3 protein." (PMID 41458630, 2025). "Plasmids expressing full-length NPAS3, either wild-type (WT) or V304, were therefore expressed in SH-SY5Y human neuroblastoma cells." (PMID 34834422, 2021). "Besides, in human neuroblastoma SH-SY5Y cells and rat pheochromocytoma PC12 cells, cell proliferation was significantly increased following Npas3 overexpression and decreased following Npas3 knockdown." (PMID 36313621, 2022).
malignant glioma (2 papers, 2022 to 2025). A grade III or grade IV glioma arising from the central nervous system. "Overexpression of NPAS3 in malignant glioma cell lines dramatically slowed transformation, whereas lower expression spurred more aggressive development." (PMID 40535770, 2025).
amyotrophic lateral sclerosis (1 paper, 2021). Amyotrophic lateral sclerosis (ALS) is a neurodegenerative disease characterized by progressive muscular paralysis reflecting degeneration of motor neurons in the primary motor cortex, corticospinal tracts, brainstem and spinal cord. "Indeed, by analogy with proteins that form aggregates in neurodegenerative conditions such as amyotrophic lateral sclerosis, it seems likely that a variety of mutations, spontaneous or familial, could impact NPAS3 aggregation, of which V304I is simply one." (PMID 34834422, 2021).
brain tumor (1 paper, 2013). "Variants of NPAS3, a neuronal transcription factor thought to be involved in brain tumor suppression, were found to be associated with 11 of the MetS phenotypes (Fatkg, Leankg, SubQF, TAF, REE, TG, TC, LDL-c, pulse, IL1b and IL-6), suggesting a pleitropic effect." (PMID 23628382, 2013).
breast carcinoma (1 paper, 2025). "Although NPAS3 was historically connected to neurogenesis, it has emerged as a predictive hallmark for triple-negative breast cancer as a tumour suppressor that drives the progression of breast cancer via the modulation of autophagy." (PMID 40535770, 2025).